ANXA5 (annexin A5)
Diseases named in the same sentence as ANXA5 in open-access papers (continued):
Sharing a sentence is not in itself a finding about the gene and the disease.
tumor (continued). "The authors conclude that visual evaluation of 99mTc-HYNIC-Annexin A5 tumor uptake appears to be a reliable method to detect early treatment-induced apoptosis and predict tumor response." (PMID 24216991, 2013). "99mTc-HYNIC-Annexin A5 tumor uptake 5 to 6 h PI is thus a good reflection of ongoing apoptosis in vivo, but only in tissues with no or minimal necrosis." (PMID 24216991, 2013). "They studied the relation between baseline tumor tissue uptake of 99mTc-HYNIC-Annexin A5 and apoptosis." (PMID 24216991, 2013). "99mTc-HYNIC-Annexin A5 tumor-to-background ratio (T/N) was found to be significantly higher in responders compared to non-responders." (PMID 24216991, 2013). "The authors found that 99mTc-HYNIC-Annexin A5 tumor uptake 5 to 6 h post injection (PI) correlates statistically significant with the number of apoptotic cells found by TUNEL assays when samples with no or minimal amounts of necrosis are considered." (PMID 24216991, 2013). "The injection of irradiated tumor cells pre-incubated with AnxA5 cured established tumors in about 50% of the animals, while the injection of irradiated tumor cells only resulted in less than 10% of tumor free mice." (PMID 22848871, 2012). "Since RT induces tumor cell death and thereby the exposure of PS on dying tumor cells and on tumor blood vessels, it represents an adequate combination partner with PS-targeting agents such as AnxA5, and monoclonal antibodies such as the murine 2aG4 antibody." (PMID 22848871, 2012). "Imaging showed a statistically significant increase in the tumor binding potential of [11C]-AnxA5-ST after doxorubicin, which was even larger if compared to [11C]-mTrx-GFP-ST." (PMID 22870292, 2012). "In vivo experiments with immune competent mice bearing syngeneic tumors have proven that AnxA5 increases the immunogenicity of tumor cells." (PMID 22848871, 2012). "The growth of syngeneic tumors is significantly retarded by a single injection of AnxA5 around the tumor." (PMID 22848871, 2012). "The injection of irradiated tumor cells pre-incubated with AnxA5 cured established tumors in about 50% of the animals, while the injection of irradiated tumor cells only resulted in <10% of tumor free mice." (PMID 23251903, 2012). "The addition of AnxA5 to irradiated apoptotic tumour cells, used as tumour vaccine, increased the percentage of tumour-free mice in syngeneic tumour models and AnxA5 alone led to a retardation of syngeneic tumour growth." (PMID 20032867, 2009). "We also observed that tumour size of allogeneic CT26 colorectal tumor cells regressed faster compared to AnxA5 KO mice." (PMID 20032867, 2009). "Besides, the results of tumor microenvironment analysis suggested that ANXA5, STAT1, CD44, CAV1, and ANXA2 expression was positively correlated with the infiltration of B cell, CD8+ T cell, CD4+ T cell, macrophages, neutrophils, and dendritic cells." (PMID 40607003, 2025). "Moreover, results from the IHC assay displayed that Ki67 levels of tumor tissues were decreased by ANXA5 down-regulation in the xenograft model." (PMID 40607003, 2025). "Higher expression levels of ANXA5 were also identified as promoting tumor angiogenesis in GC." (PMID 40124374, 2025). "The preliminary validation of ANXA5 in predicting the survival rates of GC patients at 1 year, 3 years, and 5 years, as well as its expression levels were higher and role in promoting tumor angiogenesis in GC through immunohistochemistry and angiogenesis experiments." (PMID 38287304, 2024). "Some blocking strategies consist of the administration of PS ligands such as Annexin A5 (AnxA5) or others, which may slow tumor progression and increase the immunogenicity of tumor cells." (PMID 38573347, 2024). "ANXA5 could serve as a potential predictive biomarker for tumor development, metastasis and invasion, and could hold a prognostic and therapeutic significance for cancer." (PMID 39796643, 2024).
tumor (continued). "Furthermore, we have identified the pivotal gene ANXA5 gene via comprehensive analysis and substantiated its involvement in enhancing tumour cell migration through in vitro experiments." (PMID 39400959, 2024). "Moreover, tagging tumor antigens to AnxA5 significantly enhanced its immunogenicity and anti-tumor efficacy when administered after chemotherapy, which as expected increased PS exposure." (PMID 38573347, 2024). "Such correlations suggest that ANXA5 may regulate the tumor microenvironment by influencing these immunomodulators." (PMID 38287304, 2024). "ANXA5 was expressed at a low to medium level in both tumor and stomach normal tissues." (PMID 39606245, 2024). "On a molecular scale, ANXA5 increases tumor cells’ immunogenicity in different ways." (PMID 36611989, 2023). "The significance of stable α-SMA ACIs during drug treatments remains unknown but might be due to temporal differences in annexin A5 expression relative to tumor cells." (PMID 36282600, 2022). "Furthermore, ANXA5 administration in mice enhanced immunogenicity by binding to PS and inducing systemic cytotoxic T-cell responses, leading to tumor regression and reduced relapse." (PMID 36247003, 2022). "Notably, many genes were differentially expressed in virtually all cell types, such as ANXA5, which were downregulated in almost all tumor cell types." (PMID 36186437, 2022). "ANXA5 can regulate phosphatidylserine (PS)-mediated immunosuppression by binding to PS, increasing the immunogenicity of apoptotic cells, thereby enhancing the immunosuppression of the tumor microenvironment." (PMID 34512630, 2021). "The ANXA5-PS-mediated endocytic pathway was reported in living tumor cells and activated cells." (PMID 34131110, 2021). "To evaluate the influence of AnxA5 administration on the therapeutic antitumor efficacy and immunogenicity of tumor-specific immunization following cisplatin treatment, we utilized a well-established preclinical tumor model with defined tumor-specific antigen, the TC-1 tumor model." (PMID 32111835, 2020). "Similarly, an increase in the TNF-α and IL-12 cytokine levels and a decrease in TGF-β cytokine level were observed in the TME of TC-1 tumor-bearing mice treated with cisplatin and AnxA5 as compared to those treated with cisplatin only." (PMID 32111835, 2020). "Interestingly, treatment with AnxA5 resulted in the generation of slightly stronger systemic and tumor-infiltrating E7-specific CD8+ T cell responses compared to treatment with other checkpoint inhibitors." (PMID 32111835, 2020). "Furthermore, AnxA5 administration following cisplatin treatment enhanced the frequency of CD40hi and CD80hi dendritic cells (DCs) in the tumor draining lymph nodes, as well as the migration of DCs from the TME to these draining lymph nodes." (PMID 32111835, 2020). "Furthermore, a recent study in a lung tumour-bearing mouse model has also shown that fusing a tumour antigen peptide to annexin A5 (AnxA5) significantly enhances its immunogenicity and anti-tumour efficacy when administered after chemotherapy." (PMID 33114183, 2020). "Although our paper focuses on the ability of AnxA5 to act as an immune checkpoint inhibitor against PS-induced tumor immune suppression, our findings also support the importance of potent, localized antigen-specific immune responses for effective cancer treatment." (PMID 32111835, 2020). "In our proteomics study, we have found a ubiquitous and over-expressed presence of ANX1A and of two isoforms of ANXA5 which are known to play an anti-apoptotic role and are thought to be involved at different levels in the tumor development, progression and invasivity." (PMID 28686225, 2017). "The increase in surface PS has led to the use of a number of proteins or peptides that bind to PS to study apoptotic and tumor cells; among these are annexin A5 (ANXA5), an endogenous anticoagulant protein, and lactadherin (MFGE8), a major glycoprotein in milk that promotes cellular adhesion." (PMID 27160923, 2016).
tumor (continued). "Annexin A5 which is a calcium- and phospholipid-binding protein interacts with a metastasis-related protein, polycystin-1 both in vitro and in a cell culture model and induces suppression of tumor metastasis." (PMID 27929413, 2016). "Hence, the optimal time-point for tumor-imaging would be around 6 hours after injection of labeled anxA5." (PMID 24801051, 2014). "Systemic administration of Annexin-A5 or other phosphatidylserine ligands may help slow down tumor progression by blocking the tumor-supportive properties of apoptotic cells." (PMID 24860574, 2014). "In combination with radio- or chemotherapy, Annexin-A5 could be used as a natural adjuvant, which increases the immunogenicity of dying tumor cells and, thus, helps elicit an anti-tumor immune response." (PMID 24860574, 2014). "Biodistributions of anxA5, M1234, anxA5-NP en M1234-NP were determined in tumor-bearing mice." (PMID 24801051, 2014). "AnxA5 accumulated more in the tumor than M1234 while this was reversed for anxA5-NP and M1234-NP." (PMID 24801051, 2014). "Firstly, we measured tumor-uptake of anxA5 and M1234 by non-invasive imaging." (PMID 24801051, 2014). "The kinetics of tumor-uptake of AnxA5-NP and M1234-NP markedly differed from those of the monomers." (PMID 24801051, 2014). "Patients with a CR or PR showed a significant increase in 99mTc-HYNIC-Annexin A5 tumor uptake ASOT." (PMID 24216991, 2013). "Although both the serum markers and PET imaging of tumor uptake with [11C]-AnxA5-ST displayed statistically significant increases with treatment, the serum markers gave higher magnitude in their increases and would thereby likely show better sensitivity in cell death detection." (PMID 22870292, 2012). "Interestingly, the increases in the levels of the serum K18 biomarkers – and in particular ccK18 (the M30 ELISA analyte) - were clearly larger than the increases in tumor binding potential for [11C]-AnxA5-ST." (PMID 22870292, 2012). "However, in contrast to the drug-induced increases in [11C]-AnxA5-ST uptake, the tumor uptake of [18F]-FDG was unchanged at 72 hrs after the doxorubicin treatment, as compared to untreated mice or compared to [11C]-mTrx-GFP-ST." (PMID 22870292, 2012). "Combination of RT with AnxA5 resulted in the most effective inhibition of tumor growth." (PMID 22848871, 2012). "This suggested that both the [11C]-AnxA5-ST tumor binding potentials and ccK18 levels in plasma could be used as reliable biomarkers for therapy-induced cell death." (PMID 22870292, 2012). "The combination of RT with AnxA5 resulted in the most effective inhibition of tumor growth." (PMID 23251903, 2012). "In the FaDu tumor model used here, the amplitude of increased uptake of [11C]-AnxA5-ST following doxorubicin treatment was similar to that which could be expected from the extent of increase in the number of apoptotic cells in tissue at that time point." (PMID 22870292, 2012). "We found that the disruption of the c1earance of apoptotic tumour cells by AnxA5 may trigger a pro-inflammatory response contributing to a specific immune reaction against tumor cells." (PMID 20032867, 2009). "Blocking the clearance of apoptotic tumour cells by exogenous AnxA5 may open a new strategy for developing tumour vaccines." (PMID 20032867, 2009). "Moreover, the validation of ANXA5 expression in large tumor samples needs to be further studied." (PMID 40607003, 2025). "Besides AnxA5, antibodies against PS were tested in tumor models." (PMID 38573347, 2024). "For example, some studies have coupled doxorubicin with AnxA5, and its tumor-killing effect is stronger than that of either agent alone, suggesting that AnxA5 may enhance the antitumor effect of doxorubicin by targeting tumor vascular endothelial cells and tumor cells." (PMID 38474114, 2024). "Similarly, in glioma cells, ANXA5 upregulation promoted invasiveness of tumor cells." (PMID 37520464, 2023).
tumor (continued). "In addition, in vitro experiments have shown that ANXA5 depletion may hamper proliferation, migration, invasion and metastasis formation in various tumor cells from breast cancer, uterine cervical carcinoma, hepatocarcinoma and cholangiocarcinoma." (PMID 36247003, 2022). "Moreover, administration of anxA5 combined with chemotherapy or tumor vaccine (specific tumor-derived peptides) was shown to strongly improve the outcome of treatment, and only the combination of all three resulted in tumor regression and survival." (PMID 34405304, 2021). "Hence, targeted delivery of AnxA5 could be utilized to selectively inhibit tumour growth and progression." (PMID 33810523, 2021). "Thus, CORO1A, DPP4 and ANXA5 might play the significant roles in some common biological process of tumor." (PMID 33407865, 2021). "In addition, it has been shown that the binding of AnxA5 to PS+ apoptotic cells can modulate the PS-mediated immunosuppressive clearance, thereby increasing the immunogenicity of apoptotic cells, including irradiated, apoptotic-tumor cells." (PMID 32111835, 2020). "Thus, it was suggested that in combination with radio- or chemotherapy, annexin A5 could be used as a natural adjuvant to increase the immunogenicity of dying tumor cells thereby promoting the development of an anti-tumor immune response." (PMID 28824635, 2017). "Timing of imaging is one of the critical parts of the protocol because the cell death response of the tumor may occur between 1 and 48 hours after start of treatment depending on cancer type and treatment regimen and because anxA5 is rapidly cleared from the circulating blood." (PMID 24801051, 2014). "The time-courses of tumor uptake of both anxA5 and M1234 could be fitted almost perfectly with a 3-compartment model assuming exchange between blood (compartment 1) and tumor interstitium (compartment 2) and between tumor interstitium and tumor PS-target (compartment 3)." (PMID 24801051, 2014). "Targeting of externalised phosphatidylserines (PS) using annexin A5 (anxA5) is relatively unspecific because it will detect not only apoptotic cells but also, for instance, necrotic cells, ageing cells, hypoxic cardiomyocytes, tumour blood vessels and intravascular thrombi." (PMID 22541756, 2012). "The results showed that ANXA5, MMP1, MTR, REN, SCN4A, and SMAD3 were upregulated in HC samples, while HP and ACOX1 were downregulated in tumor tissues." (PMID 38599581, 2024). "Annexin A5 (ANXA5) serves as a protein kinase C inhibitor and has been shown to play a role in the progression of various tumours beyond BLCA." (PMID 39400959, 2024). "Over-expression of ANXA5 promotes malignancy and lymph node metastasis in mouse HCC cells and is a potential marker of malignant tumours and lymph node metastasis." (PMID 38049741, 2023). "The exceptions are ANXA5, ANXA6, ANXA10 and ANXA11, which play roles in several tumour types, while other ANXA members promote tumour cell proliferation." (PMID 36936694, 2023). "Our data also revealed that ANXA5 overexpression reduces the expression of EMT-related genes, suggesting possible beneficial effects of ANXA5 in inhibiting metastasis and expansion of CRC tumor cells." (PMID 37520464, 2023). "ANXA5 expression was previously found elevated at both mRNA and protein levels in 22 pairs of RCC tissues and high ANXA5 expression promotes tumor progression and poor prognosis in RCC." (PMID 37464398, 2023). "On the one hand, it has been established that ANXA5 increases tumor cell immunogenicity when fused with tumor antigens, whereas in DLBCL in vitro models, ANXA5 inhibition sensitizes tumor cells to CHOP." (PMID 36611989, 2023). "The GEPIA results showed that SERPINE1, ANXA5, F2R, and VWF increased significantly in tumor tissue." (PMID 36105100, 2022).
tumor (continued). "Annexin A5 is involved in apoptosis and downregulation of the phosphatidylinositol 3-kinase (PI3K)/Akt/NF-kB signalling pathway in certain tumours and has been demonstrated to inhibit cPLA2 in peripheral blood lymphocyte cell lines." (PMID 36050729, 2022). "The Hub gene was identified and constructed based on 6 genes (KLRB1, KLF2, S100A9,MSC,ANXA5 and IMPDH1), which will help to for a predictive analysis of the tumor immune microenvironment in HCC patients." (PMID 35992798, 2022). "The expression of ANXA5, GAS6, and MAPK1 in the tumor cells was significantly higher than that in the normal cell line." (PMID 36212395, 2022). "Likewise, AnxA5 administration lessened the immunosuppressive properties of the tumour microenvironment generated by cisplatin treatment and enhanced the immunogenicity and anti-tumour efficacy in a preclinical tumour model with a defined tumour-specific antigen (TC-1 tumour model)." (PMID 33810523, 2021). "Patients overexpressing ANXA5, FKBP10, MSN, and PYGL in the tumor tissues had significantly shorter OS compared to the low expressed group in IS1–IS3 subtypes." (PMID 34512630, 2021). "In this context, cisplatin treatment can activate TGF-β to create an immunosuppressive TME and annexin A5 works as an immune checkpoint inhibitor to reprogramme the TME and restore tumour sensitivity by blocking the expression of TGF-β3." (PMID 33114183, 2020). "We fused AnxA5 with the AH5 peptide sequence (SPSYAYHQF), a reported tumor antigenic epitope of CT26, to generate the AnxA5-AH5 fusion protein." (PMID 32111835, 2020). "CAPG, together with ANXA5 and FABP4, was previously found within a group of biomarkers differentiating invasive from noninvasive MM rat tumor models, their abundance being very significantly increased and decreased, respectively." (PMID 32867073, 2020). "Recently, AnxA5 expression in CD4 T cells has been shown to be involved in regulatory function and anti-tumor immunotherapy." (PMID 33644036, 2020). "Furthermore, due to the contribution of PS to immunosuppressive TME, AnxA5 may serve as a potential immune checkpoint inhibitor to enhance the immunogenicity of tumor-antigen specific immunotherapies, particularly following the administration of cytotoxic chemotherapeutics." (PMID 32111835, 2020). "Here we show that administration of AnxA5 alleviates the immunosuppressive properties of TME generated by chemotherapy and enhances the immunogenicity and antitumor efficacy of tumor antigen-specific immunization." (PMID 32111835, 2020). "Our work showed the positive correlations of ANXA5 level with CRKI/II and RAC1, critical molecules in integrin pathway, in tumorous tissues from HCC patients." (PMID 29802377, 2018). "A tissue microarray composed of 46 paired tumorous and adjacent normal tissues from HCC patients was employed to address the expression alteration of ANXA5." (PMID 29802377, 2018). "Mutual inter-positive correlations were apparently established for the levels of ANXA5, CRKI/II and RAC1 in tumorous tissues from patients." (PMID 29802377, 2018). "These genes are known to be implicated in proliferation (MAPK8), metastatic diffusion of tumor cells (ITGB1), drug resistance (ANXA1), coagulation (ANXA3, ANXA5) or inflammation (HPGD, NFKB1)." (PMID 29228619, 2017). "The concentration of annexin-A5-positive EVs was 3- and 6-fold higher following DOX and PDT, respectively, as compared to healthy control mice and untreated tumor-bearing mice." (PMID 27752092, 2016). "The plots of the histograms of the heterogeneity contributions in the whole tumour volume illustrate that there are more deviations from the mean or a larger frequency in the deviations for mTrx-GFP compared to AnxA5." (PMID 26501820, 2015).